CD14 (CD14 molecule)
Diseases named in the same sentence as CD14 in open-access papers (continued):
Sharing a sentence is not in itself a finding about the gene and the disease.
Sepsis (continued). "In the present study, we showed that ASCs regulate the levels of CD14++CD16+ monocytes from sepsis patients via production of PGE2." (PMID 28446249, 2017). "On the other hand, CD14++CD16– cells were significantly lower in the sepsis group (75.0% vs 90.4%, p < 0.001)." (PMID 28446249, 2017). "They compared TNF-α production and CD14 expression on monocytes among patients with severe sepsis, septic shock or cardiogenic shock as well as in healthy volunteers." (PMID 28274246, 2017). "The percentage of CD14+CD16++ cells in sepsis patients was somewhat higher than in healthy volunteers, but was statistically insignificant (5.8% vs 3.6%, p > 0.05)." (PMID 28446249, 2017). "HMGB1 further plays an important role in sepsis by facilitating the transfer of LPS to CD14 to initiate a TLR4-dependent proinflammatory response." (PMID 29261777, 2017). "ASCs transform monocytes of sepsis patients from CD14++CD16+ into the CD14++CD16– phenotype via a PGE2-dependent mechanism." (PMID 28446249, 2017). "On the other hand, the expression of CD14++CD16– monocytes was significantly increased in sepsis patients after coculture with ASCs (75.0% vs 86.0%, p < 0.001)." (PMID 28446249, 2017). "ASCs switch monocytes of sepsis patients from CD14++CD16+ to CD14++CD16– in vitro and modulate the production of inflammatory cytokines." (PMID 28446249, 2017). "Levels of CD14++CD16+ monocytes positively correlate with disease severity scores in the early phase of severe sepsis and septic shock." (PMID 28446249, 2017). "Monocytes from sepsis patients showed a significantly higher percentage of CD14++CD16+ cells than that of healthy volunteers (18.8% vs 7.2%, p < 0.001)." (PMID 28446249, 2017). "Coculture of ASCs with monocytes from sepsis patients for 24 h significantly reduced CD14++CD16+ expression while increasing the CD14++CD16– phenotype." (PMID 28446249, 2017). "Our results demonstrated that levels of CD14++CD16+ monocytes in the early phase of severe sepsis and septic shock correlated with APACHE II and SOFA scores." (PMID 28446249, 2017). "One of the new biomarkers for sepsis is soluble CD14, but there are limited data on its predictive value in febrile neutropenia of adult patients with hematological malignancies." (PMID 28845081, 2017). "In E. coli-induced sepsis in pigs, combined inhibition of C5 and CD14 essentially abolished the formation of all proinflammatory cytokines, extensively inhibited up-regulation of CD11b on granulocytes, and partly prevented the procoagulant state of sepsis." (PMID 27581539, 2017). "Both TLR4+896A/G and CD14-159C/T variant allele carriers shared common increased CD16+ (non-classical, inflammatory) monocyte subset–related mechanisms for increased severe sepsis risk." (PMID 27861595, 2016). "High plasma endotoxin/IL-10-related HLA-DR down-regulation and impaired phagocytosis of CD16- (classical, phagocytic) monocytes also resulted in increased severe sepsis risk among TLR4+896A/G and CD14-159C/T variant allele carriers." (PMID 27861595, 2016). "Toll like receptor 4 (TLR4), together with its co-receptor CD14, plays a central role in innate immune response after engagement with lipopolysaccharide (LPS) during sepsis by triggering a signaling cascade for inflammation." (PMID 27142532, 2016). "CD14 is an accessory receptor for TLRs, and ongoing clinical trials indicate that CD14 inhibition is a promising strategy to treat sepsis." (PMID 27311961, 2016). "Significantly, more overall previous episodes of infection, higher proportion of previous SBP episodes, and severe sepsis cases were observed in TLR4+896A/G and CD14-159C/T variant allele carriers than wild-type carriers." (PMID 27861595, 2016). "Findings of numerous investigations suggest a pivotal role for CD14 in initiating and perpetuating the pro-inflammatory response during the course of sepsis." (PMID 26020644, 2015).
Sepsis (continued). "According to previous investigations, CD14 is suggested to play a pivotal role in initiating and perpetuating the pro-inflammatory response during sepsis." (PMID 26020644, 2015). "In recent years, presepsin, a circulating molecule fragment derived from CD14, has been shown to be beneficial as sepsis marker in adults." (PMID 26720209, 2015). "We specifically inhibited the key proinflammatory components C5 and CD14 in a blinded, randomized, prospective study of porcine polymicrobial sepsis that closely mimics clinical sepsis." (PMID 26612199, 2015). "During sepsis, the classical monocyte subpopulation (CD14++ CD16−) seems to play an important part in the initial pro-inflammatory defence mechanism." (PMID 25793379, 2015). "Soluble CD14 subtype (sCD14-ST), recently re-named presepsin, was identified as a new marker for the diagnosis of sepsis in several reports." (PMID 26192602, 2015). "In order to set the stage for epigenomic studies in the future, we conducted genome-wide histone modification analysis of human CD14++ CD16- monocytes from two patients suffering from sepsis." (PMID 25793379, 2015). "Traditionally, sepsis patients display increased proportions of reprogrammed CD14+HLA-DRlow/-Co-receptorlow/- monocytes." (PMID 25992611, 2015). "THBD is a multifunctional immunomodulator and a putative sepsis marker which has recently been suggested to be a component of the LPS-receptor complex CD14/TLR4/MD-2." (PMID 25706641, 2015). "In this study, we investigated the association of TLR4 gene and CD14 gene SNPs (TLR4: rs10759932, rs11536889, rs7873784, rs12377632, rs1927907, rs1153879 and CD14: rs2563298, rs2569190) with susceptibility to sepsis." (PMID 25394369, 2014). "Genotypes GG of rs2569190 (the CD14 gene) and AT of rs4073 (the IL8 gene) were associated with a significantly increased risk of developing severe sepsis (p = 0.05 and p = 0.01)." (PMID 25000179, 2014). "A statistical significance was observed between rs11536889 in TLR4 gene and rs2563298 in CD14 gene in patients with sepsis and controls." (PMID 25394369, 2014). "GG genotype of CD14-rs2569190 and AT genotype of IL8-rs4073 were associated with a significantly increased risk of developing severe sepsis (p = 0.05 and p = 0.01)." (PMID 25000179, 2014). "Our results demonstrate that statistically significant associations with risk of sepsis were observed for the candidate rs11536889 SNP of TLR4 gene, rs2563298 SNP of CD14 gene and two haplotypes." (PMID 25394369, 2014). "In this study, we investigated the relationship between sepsis and TLR4 gene rs10759932, rs11536889, rs7873784, rs12377632, rs1927907 and rs1153879 polymorphisms as well as CD14 gene rs2563298 and rs2569190 polymorphisms in a Chinese population." (PMID 25394369, 2014). "Pep 2.5 therapy in CLP-induced sepsis decreased CD14 expression in lung tissue, indicating reduced innate immune stimulation and/or reduced immune cell recruitment as a consequence of Pep 2.5 mediated inhibition of inflammation." (PMID 23302299, 2013). "Pep 2.5 treatment resulted in a significantly decreased CD14 expression compared to sepsis-control (2.3 ± 1.7; P = 0.009)." (PMID 23302299, 2013). "CD14-expression in heart tissue was 3.5 ± 1.8 (mean ± SEM) fold higher in the sepsis-control compared to the sham group (P < 0.05)." (PMID 23302299, 2013). "In a recent sepsis study we were able to show in a late phase of human sepsis (day 3) an association of TLR2 and CD14 expression on monocytes with the cytokine hyporesponsiveness." (PMID 23414215, 2013). "Sequencing data suggested that although CD14 depleted cells (which are mainly T lymphocytes) expressed high levels of miR-4772-5p-iso, CD14+ monocytes generated a much better discriminative signal between sepsis and SIRS." (PMID 24146790, 2013).
Sepsis (continued). "In a model of early murine sepsis, we demonstrate that infusion of the newly synthesized Pep 2.5 is able to decrease pro-inflammatory plasma cytokine release and to decrease CD14 mRNA tissue expression compared to untreated controls." (PMID 23302299, 2013). "In spleen we detected maximum CD14 expression in the sepsis-control (9.1 ± 6.7; P < 0.05) compared to the sham group." (PMID 23302299, 2013). "Presepsin (soluble CD14-ST), a novel biomarker for diagnosing sepsis, is a subtype of soluble CD14, and is a 13 kDa protein that is a truncated N-terminal fragment of CD14." (PMID 24138799, 2013). "During polymicrobial sepsis, the amount of CD14 mRNA was significantly up-regulated in all genotypes." (PMID 22970242, 2012). "Recently, inhibition of CD-14 has been shown effectively to attenuate early inflammatory response in the animal model of sepsis." (PMID 22489138, 2012). "For example, although CD14+16+ cells are increased in psoriasis, inflammatory arthritis and sepsis, the differentiation fate of these cells is determined by cytokines and chemokines in the local microenvironment." (PMID 20102624, 2010). "We therefore compared the TLR2, TLR 4 and CD14 expression on blood monocytes of patients with sepsis and healthy controls." (PMID 19371402, 2009). "The monocyte expression of TLR2, TLR4 and CD14 was at all timepoints [admission (t0), day 1 (t1) day 3 (t2) and day 7 (t3)] significantly higher in patients with sepsis compared to the monocyte expression in healthy controls." (PMID 19371402, 2009). "In contrast to downregulation of TLR gene expression after LPS exposure in cell culture, sepsis in mice and humans sepsis causes an upregulation of TLR2, TLR4 and CD14 expression on blood monocytes." (PMID 19371402, 2009). "As microorganisms trigger the release of cytokines via TLR's and CD14, these receptors are thought to play a central role in the pathophysiology of sepsis." (PMID 19371402, 2009). "The precise role of TLR and CD14 regulation in sepsis should be evaluated in further clinical and experimental studies, especially before TLR blocking agents are clinically investigated." (PMID 19371402, 2009). "We suggest that combined inhibition of complement and CD14 should be further explored as a treatment regimen to reduce the overwhelming damaging inflammatory response during sepsis." (PMID 18419792, 2008). "Combined inhibition of complement and Toll-like receptors/CD14 should be explored as a treatment regimen to reduce the overwhelming damaging inflammatory response during sepsis." (PMID 18419792, 2008). "Presepsin, a soluble CD14 subtype released when macrophages and monocytes are activated as part of the human innate immune response to infection, has emerged as a promising biomarker to predict infection severity and adverse outcomes in sepsis." (PMID 42164187, 2026). "The progression from non‐sepsis to sepsis and septic shock was associated with significant changes in circulating CD14‐positive monocyte levels, independent of diabetes and obesity." (PMID 40781780, 2026). "Procalcitonin, C-reactive protein (CRP), CD14, and interleukin-6 can qualify as general sepsis biomarkers by broad applicability across all sepsis subtypes, consistently reported across adult, pediatric, and neonatal cohorts, reflecting a conserved pathophysiological role." (PMID 40478618, 2025). "Furthermore, the expression of SLC25A33 in CD14+ monocytes, which correlates with pro-inflammatory cytokine production and clinical resolution in sepsis patients, underscores the clinical significance of SLC25A33 in macrophage-mediated inflammatory diseases." (PMID 40384854, 2025). "Presepsin, a soluble CD14 subtype, is another sepsis biomarker reflecting innate immune activation." (PMID 41153245, 2025).
Sepsis (continued). "It is a soluble fragment derived from the N-terminal of an anchored glycoprotein known as CD14, which is present in the membranes of cells that participate in sepsis pathways, including granulocytes, monocytes, and macrophages, acting as a receptor for bacterial lipopolysaccharide (LPS)." (PMID 41149083, 2025). "Thus, we collected conditioned medium of CD38high and CD38low monocytes of sepsis, which were co‐cultured with CD14+ monocytes respectively." (PMID 40145840, 2025). "In addition, heatmap analysis further validated that most of the hub gene mains were most highly expressed in CD14+ monocytes from sepsis patients and higher than the control group." (PMID 39993996, 2025). "Presepsin, also known as soluble CD14, is known to be an early indicator of sepsis." (PMID 38673584, 2024). "Notably, compared to healthy controls, the expression of LGALS9 in sepsis patients was significantly reduced, particularly within the Mono_CD14 subtype." (PMID 39044269, 2024). "Presepsin is a product of the cleavage of CD14 from bacterial proteases during sepsis." (PMID 38698211, 2024). "The percentage of MO3 (CD14 + CD16 + +)/monocytes was higher in sepsis patients than in controls (P = 0.011), whereas the percentage of MO1 (CD14 + + CD16 −)/monocytes was higher in septic shock patients and 28-day death group than in those without shock and 28-day survival group (P = 0.034, 0.038)." (PMID 36721090, 2023). "On the other hand, CD14 inhibition has shown to be beneficial in attenuating the detrimental effect of complement activation and modulation of the cytokine storm in fulminant sepsis patients." (PMID 37628421, 2023). "Also, treatment with MLT decreased the liver tissue expression of the CD14 molecule observed after sepsis induction." (PMID 38203627, 2023). "Furthermore, we validated the expression of circ_0075723 in CD14+ monocytes by qRT-PCR among the three groups and found that circ_0075723 was significantly downregulated in pneumonia-induced sepsis patients comparing to the other two groups." (PMID 36923408, 2023). "Furthermore, we identified that circ_0075723 was significantly decreased in the plasma and CD14+ monocytes of sepsis patients secondary to pneumonia." (PMID 36923408, 2023). "Interestingly, Toll‐like receptor signalling was detected in sepsis, specifically in the brain (prefrontal cortex and hippocampus), via the upregulation of genes such as CD14, TLR1, TLR2, TLR3, TLR7, IRAK3 and IRAK4." (PMID 37731199, 2023). "In conclusion, we report that CD14+/CD81+ BAL EV are enriched in patients with sepsis-related ARDS compared with controls, and that an elevated CD14+/CD81+ BAL EV count is associated with increased mortality in patients with ARDS, although the sample size is modest." (PMID 35234046, 2022). "A recent study used single cell RNA sequencing to reveal a CD14+ monocyte phenotype named MS1, characterized by high expression of RETN, ALOX5AP, and IL1R2, that was unique in patients with sepsis and associated with sepsis-induced immunosuppression." (PMID 36470832, 2022). "Similar to other inflammatory and infectious conditions such as sepsis, lupus erythematosis, and rheumatoid arthritis among others, we detected statistically significant increases (P<0.002) of intermediate CD14+, CD16+ monocytes in individuals with PASC compared to healthy controls." (PMID 35082777, 2021). "According to some literatures on NAFLD, some immune-related loci associated with NAFLD could exhibit some level of pleiotropy influencing sepsis with genes of CD14, IL-6, MIF, TLR4, and TNF." (PMID 34938184, 2021). "Additionally, circulating CD14+ macrophage-derived EVs, released via P2X7 receptor activation, are linked with better survival in the CLP sepsis mouse model." (PMID 34451925, 2021). "Presepsin (soluble CD14 subtype) is a novel biomarker of sepsis." (PMID 32503419, 2020). "Presepsin (soluble CD14 subtype) is a novel biomarker of sepsis used for early diagnosis." (PMID 32503419, 2020).
Sepsis (continued). "Release of P2X7 receptor-dependent CD14 during sepsis is important for survival." (PMID 33135636, 2020). "Soluble CD14 subtype (sCD14-ST) is another promising sepsis marker which is named as presepsin." (PMID 33204274, 2020). "In sepsis caused by gram-negative bacteria, binding of LPS to the CD14 membrane receptor leads to excessive activation of monocytes and macrophages." (PMID 32230846, 2020). "Patients with sepsis often have elevated amounts of CD14 in their bloodstream." (PMID 33135636, 2020). "Altogether, our results demonstrate that the P2X7 receptor controls the release of CD14 in extracellular vesicles, impairing LPS signaling in myeloid cells and controlling bacteria and cytokine production during sepsis, thus reducing tissue damage and improving survival." (PMID 33135636, 2020). "• Reverses monocyte deactivation in sepsis by inducing HLA-DR expression • Utility in cancer patients remains to be determined. • May also promote the development of CD14+HLA-DRlo/neg monocytes, dependent on dosing, timing, and other mechanisms." (PMID 31191529, 2019). "The proportion of PMN-MDSCs and M-MDSCs, defined as CD14neg/low CD64low CD15+/low LDG and CD14+ CD64+ HLA-DRneg leukocytes, may vary according to causative agent leading to sepsis." (PMID 30873175, 2019). "Notably, the observed changes occurred despite both (i) different foci and (ii) varying causative pathogens of sepsis in our study collective, pointing towards a common, robust and specific MHC-II regulatory phenotype in immune-compromised CD14++ monocytes." (PMID 30212590, 2018). "Similarly, CD14 plays a crucial role in initiating and perpetuating the pro-inflammatory processes during sepsis." (PMID 28149700, 2017). "CD14-159C/T polymorphism is not relevant to sepsis mortality in any genetic models, regardless of the ethnicities." (PMID 28122493, 2017). "However, the percentages of CD14+CD16++ cells were unaffected by coculture with ASCs in both sepsis patients (5.8% vs 3.7%, p > 0.05) and healthy volunteers (3.6% vs 3.5%, p > 0.05)." (PMID 28446249, 2017). "Also, soluble CD14-st (presepsin) has been considered as a promising biomarker because of its rapid increase at the early stages of sepsis and the availability for bed-side analysis." (PMID 28845081, 2017). "The findings in the present study indicate that CD14++CD16+ monocytes might serve as a marker for severe sepsis and septic shock." (PMID 28446249, 2017). "In the present study, we analyzed the anti-inflammatory efficacy of the pheophytin-b on both RAW 264.7 murine macrophage and purified human CD14+ monocytes stimulated with lipopolysaccharide (LPS) and elucidated the mechanisms by analyzing the cell signaling pathways known to be activated in sepsis." (PMID 29211014, 2017). "In comparison with healthy controls, higher frequencies of TLR4+896A/G and CD14-159C/T variant alleles were noted among severe sepsis and non-severe sepsis febrile de-compensated cirrhotic patients as well as afebrile compensated cirrhotic patients." (PMID 27861595, 2016). "Among both TLR4+896A/G and CD14-159C/T variant allele carriers with severe sepsis, a significant negative correlation was found between plasma endotoxin level and LPS-stimulated HLA-DR expression on CD16- monocyte." (PMID 27861595, 2016). "Among cultured CD16- monocytes collected from cases carrying wild-type TLR4+896A/G or CD14-159C/T allele and non-severe sepsis, acute LPS incubation significantly stimulated HLA-DR/mCD14 expressions and phagocytosis." (PMID 27861595, 2016). "Collectively these data suggest that WISP1-αvβ3 integrin signaling is involved in TLR4 pathways in macrophages and may be an important contributor to TLR4/CD14 mediated inflammation in sepsis induced lung injury." (PMID 27349568, 2016).